CASP8 (caspase 8)
Diseases named in the same sentence as CASP8 in open-access papers (continued):
Sharing a sentence is not in itself a finding about the gene and the disease.
colorectal cancer (continued). "This protein is up-regulated in human colorectal cancer and by interacting with the antiapoptotic protein Caspase 8 (CASP8) and FADD like apoptosis regulator (CFLAR, also known as c-FLIP), it plays a key negative role in apoptosis." (PMID 33233365, 2020). "Overall, our findings provide evidence that EGCG can be a sensitizer of TRAIL via DR5 and caspase 8 mediated apoptosis in colorectal cancer cells." (PMID 32283836, 2020). "Different types of mutations in CASP8 have been detected in different cancer tissues such as HNSCC, hepatocellular, gastric, and colorectal carcinomas." (PMID 32492030, 2020). "The first aim was to obtain evidence for the actual expression of Bcl2, Bad, BAX, caspase-8, and caspase-9 in pancreatic and colorectal carcinoma cells." (PMID 30686270, 2019). "Both early and late stage colorectal cancer cell lines were found to have higher caspase-8 activity post transfection with siRPSA #1, in contrast to cells that were not transfected." (PMID 29843646, 2018). "It was recently shown that the ring finger domain has E3 ubiquitin activity that targets caspase-8 and -10 in death receptor–mediated apoptosis, and that exogenous overexpression of hRFI in colorectal cancer cells inhibits the extrinsic apoptotic pathway." (PMID 28902127, 2017). "Our results show significant changes of caspase 8 and 9 in all colorectal cancer cell lines, while caspase 3 was increased significantly only in CC-531 cells." (PMID 11875713, 2002). "Prior work in colonic epithelial and colorectal cancer models has established that PAR-2 activation exerts robust anti-apoptotic effects, whereas PAR-2 silencing or pharmacologic inhibition restores caspase-8/-3 activation and enhances susceptibility to cytokine- or chemotherapy-induced apoptosis." (PMID 41596561, 2026). "In certain colorectal cancers, CASP8 is inactivated, which could lead to the amplification of necroptosis and PANoptosis pathways." (PMID 40422233, 2025). "However, the expression of caspase-8 and caspase-9 was evaluated in patients with colorectal cancer." (PMID 33919909, 2021). "Our results indicated that NOV may sensitize the inhibitory effect of 5-Fu on colorectal cancer via the JNK/AP-1/Caspase-8/Caspase-3 pathway." (PMID 35201461, 2021). "Moreover, the relative activity of caspase-8 of cancer cells (human colorectal carcinoma cells - HCT-116) treated with these fatty acids was significantly higher than that found in control cells." (PMID 30850631, 2019). "Our observation of elevated Bax expression and an increase in caspase-8 activity in 3c treated colorectal cancer cells may suggest involvement of extrinsic apoptotic pathway as well." (PMID 28049506, 2017). "Therefore, in colorectal cancer cells the DRE treatment must have utilized caspase-8 independent cell death pathway." (PMID 27564258, 2016). "Furthermore, Sp1 and Elk-1 bind to the caspase-8 promoter and induce apoptosis in colorectal cancer cells in response to SPARC treatment." (PMID 25693514, 2015). "Genotypes of the three CASP8 gene promoter variants in Han Chinese with and without colorectal cancer." (PMID 23844036, 2013). "However, our data are in accordance with a recent pilot investigation, reporting, albeit with borderline statistical significance, a negative prognostic impact of the CASP8 -652 6N Del allele for colorectal cancer patients." (PMID 27507139, 2016). "To investigate the specific cell death pathways activated by compound 12, we conducted Western blot analyses focused on the expression levels of caspase-3, caspase-8, and caspase-1 in HCT-116 colorectal carcinoma cells." (PMID 41155897, 2025). "For instance, in colorectal carcinoma (CRC) with the BRAF V600E mutation (8% of CRC cases), treatment with CDK1 inhibitors significantly enhances the therapeutic efficacy of MEK inhibitors by reactivating caspase 8 activity." (PMID 39800748, 2025).
colorectal cancer (continued). "Specifically, CASP8, KMT2D, RPL22 and TGFBR2 alterations tended to co-occur with GIE in patients with colorectal cancer." (PMID 37165135, 2023). "In colorectal cancer HCT-15 cells, TSAIII treatment was found to induce apoptosis, as demonstrated by the activation of caspase, induction of cleaved-caspase-3, caspase-8, and caspase-9, and decreased expression of Bcl-xL and Bcl-2." (PMID 36611961, 2022). "Taken together, these findings suggest that EGCG can be a potent TRAIL sensitizer via extrinsic apoptotic pathway such as caspase 8 and DR5 activation in colorectal cancer cells." (PMID 32283836, 2020). "We were able to validate previous findings describing frequent hypermethylation events of EPHA7, MGMT and MLH1 in colorectal cancer patients, RARB in prostate tumors, and CASP8 in glioblastoma." (PMID 28581523, 2017). "It was recently shown that mRNA expressions of Caspase-9 and Caspase-3 (unlike Caspase-8) were downregulated in human colorectal cancer tissues in comparison to marginal tissues." (PMID 37108361, 2023). "However, miR-27a antioligonucleotides treatment didn't promote the activation of caspase-8 and release of cytochrome c in TRAIL-treated colorectal cancer stem cells." (PMID 28423356, 2017). "Thus, we detected the expression of caspase 3, caspase 8, and BCL-2, when AK027294 expression was significantly knocked down in colorectal cancer cells." (PMID 26820130, 2016). "In addition, in response to secreted protein, acidic and rich in cysteine (SPARC) expression, Sp1 and Elk-1 bind to the caspase-8 promoter and induce apoptosis in MIP101 colorectal cancer cells." (PMID 25693514, 2015). "Also, salinomycin induces apoptosis in cisplatin-resistant human colorectal cancer cells (Cisp-resistant SW620 cells) by increasing the protein expression of caspases 3, caspase 8, caspase 9 and BAX, but decreasing the protein expression of Bcl-2." (PMID 25531367, 2014). "Therefore, in order to further study the mechanism of RES and VE in promoting colorectal cancer cell apoptosis, western blotting was performed to detect the expression of BCL-2, BAX, caspase-3-, caspase-8-, and caspase-9-related proteins after RES and VE intervention." (PMID 34803703, 2021). "However, no caspase-8 activation was detected suggesting that PT induced intrinsic apoptotic pathway in colorectal cancer cells." (PMID 32703189, 2020). "Colorectal cancer cell lines were selected because they exhibited variable sensitivity to MEDI3039 in the cell line screen and interestingly CASP8 mRNA expression alone did not predict for sensitivity to MEDI3039, despite a biomodal pattern of sensitivity." (PMID 35086954, 2022). "Moreover, a significant correlation between the CASP8/MCL-1 protein ratio and sensitivity to MEDI3039 was observed in the colorectal cancer panel, although this failed to reach significance at the mRNA level." (PMID 35086954, 2022).
prostate carcinoma (70 papers, 2007 to 2026). A carcinoma that arises from epithelial cells of the prostate gland. "As for prostate cancer, CASP8 has been shown to have potential as a marker for high-risk prostate cancer." (PMID 40149637, 2025). "Our study identified CASP8 as a promising protein biomarker for detection of high-risk prostate cancer and potentially renal cancer." (PMID 33828176, 2021). "Our study nominates CASP8 as a candidate biomarker for diagnosis of high-risk prostate cancer and warrants further large cohort validation studies." (PMID 33828176, 2021). "Yet the associated CASP8 transcriptional anomalies are similar in all three corresponding normal tissues and in breast and prostate cancers." (PMID 26740556, 2016). "Using these methods, we have found that the insertion of an SVA-E retrotransposon into the CASP8 gene is associated with transcript anomalies and protects against prostate cancer." (PMID 26740556, 2016). "A previous study has shown that ethnic-specific differences were evident in the association of CASP8-625 6N del and D302H polymorphisms with prostate cancer risk in east Asian and Indian populations." (PMID 27821804, 2016). "Study showed that histidine variant of CASP8 D302H is a protective allele for aggressive prostate cancer." (PMID 23554680, 2011). "To explore the potential association between the CASP8 -652 6N ins/del polymorphism and prostate cancer risk in a Chinese population, we performed a hospital-based case-control study with 406 prostate cancer cases and 408 cancer-free controls." (PMID 23554680, 2011). "In conclusion, this study identified that the CASP8 -652 6N ins/del polymorphism was associated with reduced risk of prostate cancer in a Chinese population." (PMID 23554680, 2011). "In the present study, we found that the CASP8 -652 6N ins/del polymorphism was associated with reduced risk of prostate cancer in a Chinese population." (PMID 23554680, 2011). "In this study, we identified that the CASP8 -652 6N ins/del polymorphism was associated with reduced risk of prostate cancer." (PMID 23554680, 2011). "This is the first study of the association between CASP8 -652 6N ins/del polymorphism and prostate cancer risk in Chinese population." (PMID 23554680, 2011). "It has been reported that CASP8-652 6N ins/del polymorphism may affect the susceptibility to prostate cancer and reduce the risk of prostate cancer in Chinese men, while in other cancers it may be associated with cell death and tumor growth." (PMID 40149637, 2025). "Given the positive relationship between caspase 8 and prostate cancer, S_Alistipes_shahii should be associated with a decreased risk of prostate cancer, which contradicted the MR results between gut microbiota and prostate cancer." (PMID 39882449, 2024). "Together, our results suggest that CASP8 may potentially serve as a biomarker for high-risk prostate cancer and possibly renal cancer." (PMID 33828176, 2021). "Thus, rs700635[C] is associated with protection against prostate cancer, failure to correctly splice CASP8 intron 8, and with the presence of the SVA-E retrotransposon in the intron." (PMID 26740556, 2016). "The results of SMR analysis indicated that CASP8 could increase the risk of prostate cancer." (PMID 40149637, 2025). "We examined by genotyping whether the -652 six-nucleotide insertion-deletion (6N ins/del) polymorphism in the CASP8 promoter region was associated with prostate cancer risk in a hospital-based case-control study of 406 Chinese prostate cancer patients and 408 age-matched cancer-free controls." (PMID 23554680, 2011). "Subsequently, we explored the role and mechanism of CASP8 in prostate cancer cells and defined a new cell type: the CASP8 T cell." (PMID 40149637, 2025). "In conclusion, CASP8 can be used as a potential biomarker for prostate cancer and provide an effective prognosticator for the risk grade of BCR in prostate cancer, facilitating early-stage personalized treatment and improving prognosis." (PMID 40149637, 2025).
prostate carcinoma (continued). "Although we explored the expression characteristics and prognostic role of the CASP8 gene in prostate cancer and achieved certain results, there are still limitations." (PMID 40149637, 2025). "Reverse chronological analysis revealed that CASP8+ T cells were located at the developmental end point of prostate cancer cells." (PMID 40149637, 2025). "CASP8, an Anoikis gene, has an important role in a variety of cancers, including breast cancer, lung cancer, bladder cancer, and prostate cancer." (PMID 40149637, 2025). "Caspase-3, caspase-8, Bax, and Bcl-2 levels for compounds 4c, 4e, and staurosporine on prostatic cancer (PC-3) cell line." (PMID 38257358, 2024). "Treatment of prostate cancer LNCaP with 50 μM of 20(S)-25-methoxyl-dammarane-3β,12β,20-triol for 24 h led to activation of caspase-8 and caspase-9." (PMID 39274939, 2024). "Regarding the intrinsic and extrinsic apoptosis pathways in prostate cancer, the extrinsic pathway is preferentially triggered by death receptors and activates caspase-8, which directly activates caspase-3 to induce apoptosis." (PMID 37298192, 2023). "Recently, circulating CASP8 was identified with high expression in pre-operative serum samples of prostate cancer." (PMID 37228491, 2023). "Confocal immunofluorescence assay confirmed that cryptocaryone triggered the aggregation of death receptors and recruited FADD and procaspase-8, resulting in the activation of caspase-8 and caspase-3 and apoptosis in prostate cancer cells." (PMID 36015177, 2022). "In this regard, the present work aimed to fabricate bismuth oxide nanoparticle functionalized with glutamine and conjugated with TSC and to characterize its effect on prostate cancer cells and expression of CASP8, BAX, and Bcl-2 genes." (PMID 36482061, 2022). "In contrast, in enzalutamide-resistant prostate cancer cells, the activities of caspase-8 were upregulated." (PMID 36235203, 2022). "We further report that elevated levels of CASP8 protein and mRNA are detected in human prostate cancer tissues compared to benign and BPH patient tissues." (PMID 33828176, 2021). "A higher percentage of prostate cancer samples exhibited elevated protein levels of CASP8 when compared to benign prostate and BPH tissues." (PMID 33828176, 2021). "Intriguingly, CASP8 expression is higher in metastatic disease and recurrent prostate cancer, and is elevated in renal cancer and correlates with worse survival in renal cell carcinoma." (PMID 33828176, 2021). "We confirmed over-expression of CASP8 mRNA and protein in prostate cancer tissues compared to controls, which is compatible with the observed drop in serum levels after prostatectomy." (PMID 33828176, 2021). "By performing a screen for proteins in pre-operative and post-operative serum from men with high-risk prostate cancer, we identified CASP8, MSLN, FGFBP1, ICOSLG, TIE2, and S100A4 proteins as candidate biomarkers for high-risk prostate cancer." (PMID 33828176, 2021). "By analyzing transcriptome of enzalutamide-resistant prostate cancer cells, we found that resistance was conferred by a mild caspase-8 upregulation that in turn led to NF-κB activation and the subsequent upregulation of the downstream IL-8." (PMID 34482382, 2021). "Both the catechin extracts and nanoemulsions were effective in inhibiting the growth of prostate cancer cells DU-145 through activation of caspase-9, caspase-8 and caspase-3, with the cell cycle arrest at S and G2/M phases." (PMID 34071530, 2021). "In LNCaP prostate cancer cells, enzalutamide shows overexpression in caspase-8 and caspase-3, such as luteolin, quercetin, stigmasterol, and β-sitosterol." (PMID 32102219, 2020).
prostate carcinoma (continued). "A recent report also revealed a unique apoptotic pathway in which antagonism of Bcl-2 family members in caspase-9-inhibited prostate cancer cells triggers caspase-8-dependent apoptosis." (PMID 30429828, 2018). "Both lovastatin and simvastatin induced activation of caspase-8, caspase-3, and caspase-9 in prostate cancer cells." (PMID 29523174, 2018). "IL-8 was reported to attenuate TRAIL sensitivity by upregulating the endogenous Caspase-8 inhibitor cFLIP in prostate cancer cells." (PMID 26840266, 2016). "It regulates multiple downstream genes including IGFBP3 (also present in our network) which is a pro-apoptotic and anti-angiogenic protein in prostate cancer and activates caspase 3 and caspase 8, and subsequently induces cell apoptosis." (PMID 28005952, 2016). "Sulindac sulfide is also believed to mediate its antitumorigenic effects by inducing apoptosis through up-regulated DR5 and activated the caspase 8 in colon and prostate cancer cell lines." (PMID 25730901, 2015). "Collectively, our findings suggest that activation of death receptor 5 and caspase 8/3 plays a key role in ergosterol peroxide induced apoptosis in DU 145 prostate cancer cells." (PMID 25506265, 2014). "Overall, our findings suggest that ergosterol peroxide induces apoptosis via activation of death receptor 5 and caspase 8/3 in DU 145 prostate cancer cells as a cancer chemopreventive agent or dietary factor." (PMID 25506265, 2014). "Sulindac sulfide is believed to mediate its antitumorigenic effects by inducing apoptosis through an up-regulated DR5 and activated caspase 8 in colon and prostate cancer cell lines." (PMID 25068924, 2014). "In prostate cancer activation of caspase-8 following TRD treatment was described but subsequent to activation of caspase-9." (PMID 25568670, 2014). "SiRNA transfection of DR 5 also blocked upregulation of DR 5 and cleavage of PARP and caspase 8 induced by EP in DU 145 prostate cancer cells indicating that DR 5 mediates EP induced apoptosis in DU 145 cells." (PMID 25506265, 2014). "Caspase 8 inhibitor Z-IETD-FMK interrupted the cleavage of PARP induced by EP in DU 145 prostate cancer cells." (PMID 25506265, 2014). "Nevertheless, these lines of evidence reveal that treatment of caspase-9-inhibited prostate cancer cells with ABT-263 can trigger apoptosis mainly through activation of caspase-8." (PMID 25333266, 2014). "Meanwhile, we evaluated the relationship between CASP8 mRNA expression and the -652 6N ins/del genotypes in prostate cancer tissue." (PMID 23554680, 2011). "Cycloheximide has been often used in prostate cancer cell lines as a sensitizer, because it inhibits the cellular caspase-8 (FLICE)-like inhibitory protein (c-FLIP) and inhibitors of apoptosis (IAP)." (PMID 21899742, 2011). "Further, dNSurR9-C84A rendered prostate cancer cells sensitive to the proapoptotic effects of TNF-α by potentiating the upregulation of caspase-8 activity, suggesting that survivin inhibits the extrinsic pathway of apoptosis." (PMID 20920299, 2010). "Inducible caspase-8 has been shown to be effective in prostate cancer gene therapy and malignant brain tumors." (PMID 20942909, 2010). "A recent study in prostate cancer cells indicated that CASP8 plays a pathway specific role in inhibiting androgen receptor signaling." (PMID 20132554, 2010). "The major findings in our current study are that high doses of PL elicit two major apoptotic pathways in prostate cancer cells: a caspase 8-induced cascade and the unfolded protein response." (PMID 17262078, 2007). "This study provides a comprehensive characterization of Anoikis genes and CASP8 in prostate cancer." (PMID 40149637, 2025). "CASP8 expression was significantly higher in prostate cancer tissues than in normal tissues and was concentrated in T cells, which may be due to its nonapoptotic function." (PMID 40149637, 2025).